MICA (MHC class I polypeptide-related sequence A)
Diseases named in the same sentence as MICA in open-access papers (continued):
Sharing a sentence is not in itself a finding about the gene and the disease.
schizophrenia (5 papers, 2020 to 2022). A major psychotic disorder characterized by abnormalities in the perception or expression of reality. "This study investigated the association between MICA gene polymorphisms and schizophrenia in Han and Li populations in Hainan Province." (PMID 36196481, 2022). "The results of MICA‐STR genotyping showed that MICA*A5 had the highest allele frequency in both the schizophrenia patient and the control groups, which were 34.5% and 41.5%, respectively, but the difference was not statistically significant." (PMID 36196481, 2022). "After comparing the allele frequencies of the two groups, the MICA*002:01 allele frequency (18.2%) in schizophrenia patients was significantly higher than that in the healthy control group (5.3%) (the χ2 value was 9.575, and the p‐value was 0.002)." (PMID 36196481, 2022). "This is the first study that explored the role of MICA gene polymorphism in the pathogenesis of schizophrenia." (PMID 36196481, 2022). "Sequencing‐based‐typing (PCR‐SBT) technology was used for MICA allele typing, and the correlation analyses of MICA gene polymorphism and schizophrenia were performed." (PMID 36196481, 2022). "In the Li population, the MICA*010 allele frequency of schizophrenia patients was relatively higher than that of healthy controls, but the difference was not statistically significant after Bonferroni correction." (PMID 36196481, 2022). "The MICA*A002:01 allele frequency was highest in both schizophrenia and healthy controls at 23.2% and 22.9%, respectively." (PMID 36196481, 2022). "This study aimed to explore the correlation between the major histocompatibility complex class I polypeptide‐related sequence A (MICA) polymorphisms and schizophrenia." (PMID 36196481, 2022). "Second, this study only discussed schizophrenia from the MICA gene polymorphism, which has certain limitations." (PMID 36196481, 2022). "The MICA*008 allele frequency (20.2%) in patients with schizophrenia was relatively lower than that in the control group (31.9%)." (PMID 36196481, 2022). "We speculate that the MICA gene may increase the risk of schizophrenia by affecting immune regulation or fetal neurodevelopment." (PMID 36196481, 2022). "This study aimed to analyze the association between MICA gene polymorphisms and schizophrenia in Han and Li populations in Hainan Province, located at the southernmost tip of China, isolated from the mainland, where the Li and Han nationalities account for more than 98% of the province's population." (PMID 36196481, 2022). "MICA alleles may be just a part of haplotype or reflection of linkage disequilibrium, the real effect on schizophrenia may be through HLA." (PMID 36196481, 2022). "Also, further studies are needed to establish whether the MICA gene mutation is widespread in the schizophrenia population and to determine its exact pathogenesis." (PMID 36196481, 2022). "In our future studies, we plan to investigate the effect of overexpression of MICA on cell proliferation and apoptosis through corresponding cell function experiments and explore the pathophysiological relationship between MICA and schizophrenia." (PMID 36196481, 2022). "MICA‐STR genotyping indicted that MICA*A4 had the highest frequency in the schizophrenia population and healthy controls, with 33.2% and 35.4%, respectively, and the lowest frequency genotype in both groups was MICA*A6." (PMID 36196481, 2022). "Even after Bonferroni correction, the allele frequencies of MICA*002:01, MICA*A4, and MICA*A9 significantly differed between Han schizophrenia patients and Han healthy controls, indicating that these alleles may be related to the susceptibility of schizophrenia in the Han population." (PMID 36196481, 2022). "Although the correlation between MICA*007 allele frequency and schizophrenia in the Han population was not significant, it also seems to be related to schizophrenia, because it was absent in healthy controls." (PMID 36196481, 2022).
schizophrenia (continued). "Moreover, the allele frequencies of MICA*A4 (χ2 = 7.572, p = 0.006, pc = 0.030) and MICA*A9 (χ2 = 7.519, p = 0.006, pc = 0.031) in patients with schizophrenia were all different from those in healthy controls (p values <0.05 after adjusting the values)." (PMID 36196481, 2022). "Among possible targets of these eRNA candidates are ARHGEF38 and SH3YL1, which have been linked to bipolar disorder and suicide, GLRA1 and MCTP2 were found to be associated with schizophrenia, and CHIR-B3, MHCIA7, MHCIY as well as MICA are genes involved in the immune system." (PMID 32854615, 2020). "In addition, in this study, no MICA alleles significantly associated with schizophrenia in the Li population were found, which may imply that the effect of MICA on schizophrenia is associated with ethnic differences." (PMID 36196481, 2022). "This analysis revealed top genes, such as NOTCH4, MICA, TRIM27, PBX2, and FKBPL, as enriched in GWAS of schizophrenia, CLZ-induced agranulocytosis/granulocytopenia in treatment-resistant schizophrenia, and bipolar disorder among other psychiatric and non-psychiatric conditions." (PMID 35664466, 2022).
acute graft versus host disease (4 papers, 2013 to 2024). A syndrome of immunologically mediated tissue damage that may occur following an allogeneic transplant, usually affecting the skin, liver, and GI tract. "Speedy NKG2D reduction on alloreactive CD8+T cells suggested that activation of MICA-129Met diminished the severity of acute graft-versus-host disease." (PMID 38474281, 2024). "It has been found that TNF-α and γ-rays can increase MICA expression by activating the NFκB and JNK pathways in acute graft-versus-host disease, leading to graft damage." (PMID 30013574, 2018).
B-cell lymphoma (4 papers, 2020 to 2022). "We used a tumor model consisting of NOD-SCID mice bearing invasive MICA-expressing B-cell lymphomas, resulting from the intravenous (i.v.)injection of Raji-MICA*001 tumor cells." (PMID 35967081, 2021). "We then treated with metformin the primary cells from a B-cell lymphoma patient (BCL-P2) and observed that it significantly increased expression of ULBP1 and ICAM-1 and tended to increase MICA/B and CD20 expression." (PMID 35079096, 2022). "To investigate whether ADCC activity was influenced by an altered anti-MICA/B mAb-CD16 interaction, we tested the ability of an anti-CD20 mAb (rituximab, RTX) to mediate ADCC for Daudi target cells derived from a human B-cell lymphoma." (PMID 33266137, 2020).
breast tumor (4 papers, 2016 to 2021). "Fusion protein MICA-G129R when circulating into breast tumor will adhere the MICA back to the surface of breast tumor cells through the binding of the G129R to PRLR." (PMID 34077462, 2021). "Moreover, in human breast tumor-bearing nude mice, mAb04-MICA demonstrated superior anti-tumor efficacy compared to combination therapy of mAb04 + Docetaxel or Avastin + Docetaxel, highlighting the immunostimulatory effect of MICA." (PMID 26909862, 2016). "Furthermore, the involvement of NKG2D on γδ T cells and MICA/B on MCF-7 and T47D was found in cytotoxicity of γδ T cell against breast tumor targets." (PMID 34322393, 2021). "We have confirmed the involvement of NKG2D on γδTc and MICA/B on MCF-7 and T47D in cytotoxicity of γδTc against breast tumor targets, although differences in the ability of γδTc to kill targets pre-incubated in hypoxia or normoxia do not appear to be related to surface levels of MICA." (PMID 29963058, 2018).
cervical tumors (4 papers, 2009 to 2021). "Our data indicate that the cervical tumour cells express markers associated with activation of the immune system (CD95 and MICA/B), as well as markers related to inhibition of the immune system (CD73, CD39, CTLA-4, and CD25)." (PMID 31198791, 2019). "In order to elucidate this point, we addressed cell surface expression of MICA/B in various established cervical tumor cell lines known to be infected with HPV-18 (HeLa), HPV-16 (SiHa) or uninfected (C33-A)." (PMID 21631944, 2011).
cholangiocarcinoma (4 papers, 2014 to 2025). A carcinoma that arises from the intrahepatic biliary tree (intrahepatic cholangiocarcinoma) or from the junction, or adjacent to the junction, of the right and left hepatic ducts (hilar cholangiocarcinoma). "The targeting of MICA/B has given promising results in vitro in patients with cholangiocarcinoma (CCA)." (PMID 38473265, 2024).
colitis (4 papers, 2017 to 2021). Inflammation of the colon. "In this study, we investigated the frequency of LP NKG2D+ NK cells in DSS-induced colitis model and intestinal mucosal samples of UC patients, as well as the secretion of Th1/Th2/Th17 cytokines in NK cell lines after MICA stimulation." (PMID 29228739, 2017). "Colitis increases the expression of the human nonclassical MHC class I molecules MICA and MICB on intestinal epithelial cells, resulting in the migration of CD8+ T cells into the inflamed intestine." (PMID 33513946, 2021).
colorectal tumor (4 papers, 2019 to 2026). "They demonstrated that anti-MICA/B and a combination of both anti-MICA/B and anti-NKG2A antibodies were able to induce immune-mediated destruction of colorectal tumor organoids during cocultures with autologous TILs." (PMID 35450073, 2022).
dengue (4 papers, 2014 to 2025). "Multiple HLA alleles have been identified as factors of susceptibility or protection against dengue across diverse populations, including HLA class I and II alleles and proteins like MICA, MICB, and LTA." (PMID 40006967, 2025). "It still has not been determined whether the association between these NKG2D ligands and dengue clinical responses is directly due to the function of MICA/B molecules in dengue pathogenesis." (PMID 24829565, 2014). "Previous studies identified associations between MICA and MICB (MHC class I chain-related genes) within the extended major histocompatibility complex (MHC) region and hepatitis C39 and dengue virus infections, both members of the Flaviviridae family." (PMID 41377660, 2025). "Recently, genome-wide association studies have shown an association between MICB and MICA, which encode ligands of the activating NK receptor NKG2D, and dengue disease outcome." (PMID 24829565, 2014).
kidney transplant (4 papers, 2019 to 2024). A surgical procedure in which one or both kidneys from a donor are implanted into a recipient. "In 41 kidney transplant recipients, antibodies against HLA class I and II and MICA were determined sequentially, from month 0 (prior to vaccination) until month 12 post-vaccination." (PMID 39591147, 2024). "Forty-seven clinically stable kidney transplant recipients were vaccinated once with Prevenar and HLA class I and II and MICA antibodies were analyzed by LuminexTM technology (LABScreenTM Mixed Beads) prior to vaccination and at month 1 and month 12 thereafter." (PMID 31390822, 2019).
leprosy (4 papers, 2013 to 2022). Leprosy is a chronic infectious disease affecting primarily the skin and peripheral nervous system. "Recently, our group conducted a study of MICA genes and leprosy in a population of southern Brazil showing that the MICA*027 allele was decreased in leprosy per se and in MB patients." (PMID 26793196, 2015). "A study analyzed exon 5 of the MICA gene and intron 1 of MICB in families of Southern India who developed PB leprosy and showed that MICA*5A 5.1, MICB*CA16 and MICB*CA19 were associated with the disease." (PMID 26793196, 2015). "In this context, the MICA*027 allele was associated with protection against leprosy per se and the multibacillary subtypes." (PMID 23936864, 2013). "The MICA*5A5.1 allele, associated with leprosy susceptibility in this much larger study, has a single G insertion occurring in a background of five alanine repeats causing a frame shift mutation that results in a premature stop codon and a truncated transmembrane domain." (PMID 26793196, 2015). "Finally, these results suggest the influence of MICA alleles in the development of the leprosy and their clinical forms and need to be replicated." (PMID 23936864, 2013). "Summary of associations between genes of innate immune response MICA, MICB, KIR, TNF, LTA, BAT1, IFNG, and leprosy." (PMID 26793196, 2015). "While genetic studies have implicated non-classical MHC genes like LTA and MICA in leprosy susceptibility, the main effects have been assigned to classical class I and class II HLA genes." (PMID 32776973, 2020). "The frequency of the MICA*A5 allele showed a decreasing tendency in the patients with leprosy as compared to the controls, but the difference was not significant." (PMID 26793196, 2015). "MICA*027 codifies a transmembrane domain, A5, related to the normal expression of protein associated with protection against, suggesting susceptibility toward leprosy and its most severe form." (PMID 26793196, 2015). "In addition, studies have demonstrated the influence of MICA genes in the pathogenesis of leprosy." (PMID 23936864, 2013).
liver disease (4 papers, 2013 to 2018). "Until now, studies regarding the association of MICA SNP and its serum levels with liver disease mainly focus on HCC." (PMID 28427234, 2017). "The genetic factors that play a role in late-stage liver disease remain controversial, although several studies have shown that variants in MICA, DEPDC5, HCP5 and PNPLA3 affect HCC development." (PMID 28928439, 2017). "Serum MICA levels correlated with liver disease severity only in MICA rs2596542 A allele carriers." (PMID 28427234, 2017). "In conclusion, serum MICA levels were highly correlated to liver disease severity in CHC patients who carried the MICA rs738409 A allele." (PMID 28427234, 2017). "In the current study, neither the MICA SNP nor sMICA were associated with advanced liver disease among the whole population." (PMID 28427234, 2017).
liver fibrosis (4 papers, 2013 to 2023). "Consistent with the present findings in the setting of chronic HCV infection, a recent report suggests that MICA polymorphisms (MICA*012:01/02, MICA*017 and MICA*027) are associated with liver fibrosis in schistosomiasis." (PMID 30723271, 2019). "In conclusion, we have demonstrated that MICA rs2596542 is associated with liver fibrosis progression, likely mediated and amplified in part through TGFβ-1 dependent mechanisms." (PMID 30723271, 2019). "sMICA > 50 pg/mL provided a positive predictive value of 72 % in predicting advanced liver fibrosis (F3-4) and of 90% in significant fibrosis (> F2) in MICA rs2596542 A allele carriers." (PMID 28427234, 2017). "Logistic regression analysis revealed that factors associated with advanced liver fibrosis was sMICA (OR/CI: 2.996/1.428–6.287, P = 0.004) and platelet counts (OR/CI: 0.988/0.982–0.994, P < 0.001) in MICA rs2596542 A allele carriers." (PMID 28427234, 2017). "However, evidence for the association of MICA SNP rs2596542 and sMICA with liver fibrosis is sparse." (PMID 28427234, 2017). "In this regard, little is known about the potential effect of variants in MICA and DEPDC5 on liver fibrosis since both GWAS were done in patients in whom liver biopsy was not available." (PMID 30723271, 2019). "Here we sought to dissect the role of MICA rs2596542 and DEPDC5 rs1012068 to liver fibrosis and to HCV-related HCC." (PMID 30723271, 2019). "In patients with advanced hepatic fibrosis, MICA expression was significantly lower than in patients with no or mild hepatic fibrosis." (PMID 36835058, 2023). "Interestingly and consistent with the genetic data, hepatic MICA expression was significantly lower in subjects with significant hepatic fibrosis (F2–F4) compared to those with no or mild hepatic fibrosis (F0/1) (n = 94)." (PMID 30723271, 2019).
oral squamous cell carcinoma (4 papers, 2019 to 2023). "For instance, MICA*A9 allele has been proposed to confer a risk for GC, while MICA*A5.1 allele may be associated with increased susceptibility to oral squamous cell carcinoma in Japanese patients." (PMID 33868281, 2021).
ovarian tumor (4 papers, 2011 to 2025). "γδ T cell-resistant, but not susceptible ovarian tumor cells escape γδ T cell-mediated immune recognition by up-regulating pErk1/2, thereby decreasing surface MICA levels." (PMID 21935360, 2011).
vitiligo (4 papers, 2018 to 2025). Generalized well circumscribed patches of leukoderma that are generally distributed over symmetric body locations and is due to autoimmune destruction of melanocytes. "Next we performed MICA/MICB immunofluorescence staining on sections from vitiligo and control biopsy samples together with the melanocyte marker TYRP1." (PMID 30515176, 2018). "Notably, the stress molecule MHC class 1 chain-related protein A and B (MICA/MICB) that can be bound by activating NK cell receptors also showed a tendency for increased expression in vitiligo lesions (p = 0.052)." (PMID 30515176, 2018). "The upregulation of stress-ligand MICA/MICB, recognized by activating receptors on innate and innate-like T cells, imply involvement of lymphoid stress surveillance responses in vitiligo lesions." (PMID 30515176, 2018). "Moreover, PGZ significantly lowered gene expression levels of stress molecule MHC class 1 chain-related protein A and B (MICA/MICB), NKG2D ligands, whose role was recently described in vitiligo pathogenesis." (PMID 36429011, 2022). "We could clearly observe staining for MICA/MICB in dermal areas of vitiligo lesional skin but not in healthy or non-lesional skin." (PMID 30515176, 2018).
AIDS (3 papers, 2020 to 2021). A syndrome resulting from the acquired deficiency of cellular immunity caused by the human immunodeficiency virus (HIV). "Similarly, in individuals with acquired immune deficiency syndrome (AIDS), HIV-1 decreases the cell surface expression of MICA, ULBP1 and ULBP2 in infected cells through Nef protein, which decreases the susceptibility of the virus to NK cell-mediated lysis." (PMID 34400893, 2021).
alopecia areata (3 papers, 2021 to 2024). Loss of scalp and body hair involving microscopically inflammatory patchy areas. "Another study found that in alopecia areata, various immune cell lineages, including plasmocytoid dendritic cells, NK cells and T cells, along with key molecules such as interferon-γ, interleukin-15, MICA and NKG2D, contribute to the autoimmune process." (PMID 38892934, 2024). "Regarding genes involved in hair follicle IP and hair follicle collapse that occurs in alopecia areata, the genes encoding NKG2D and its ligands such as MICA and ULBP are also relevant, and they are only involved in the pathogenesis of alopecia areata and not in other autoimmune diseases." (PMID 36292745, 2022).
asthma (3 papers, 2014 to 2023). "Here, we determine the relationship between MICA and MICB and RV infection in vitro in respiratory epithelial cells and in vivo in healthy subjects and subjects with asthma." (PMID 24556715, 2014). "The present study is, to our knowledge, the first investigation of the potential role of MICA and MICB molecules in the pathogenesis of RV infection in healthy subjects and subjects with asthma." (PMID 24556715, 2014).
Autoimmune Addison's disease (3 papers, 2014 to 2020). "Of note, the polymorphic MHC class I polypeptide-related sequence A (MICA) molecule is a ligand for NKG2D and one of its variants, MICA5.1 or ICA*008, has been shown to be strongly associated with the risk of developing autoimmune Addison’s disease." (PMID 28223394, 2017).